CD4 (CD4 molecule)
Diseases named in the same sentence as CD4 in open-access papers (continued):
Sharing a sentence is not in itself a finding about the gene and the disease.
tumor (continued). "CD4+ T cells are also essential for anti-tumor responses, as they lead to DC “licensing” and initiation, thereby enhancing cross-presentation to CD8+ T cells." (PMID 38835772, 2024). "Spatial transcriptomics and multiplex protein immunofluorescence imaging showed proximity and direct cell–cell contact between CD20+ B cells and CD4+ tumor cells in CTCL TME." (PMID 39558094, 2024). "In particular, there is extensive research on CD4 + and CD8 + TIL because each represents a T-cell subset directly associated with anti-tumor immunity, functioning as helper cells and cytotoxic T cells, respectively." (PMID 39567471, 2024). "Both clusters had a higher interaction with cluster 44 within the tumor, suggesting an interaction between CD4+ and CD8+ T cells with PVMs and tumor endothelium." (PMID 39761010, 2024). "A large percentage of these ex-Th17 cells in the tumor tissue are significantly more proficient at producing pro-inflammatory cytokine IFN-γ compared to the endogenous tumor-infiltrating CD4+ T cells." (PMID 39185202, 2024). "An analysis of the tumor-infiltrating mononuclear cells in the α-gal micelle-injected lesions indicated that they include dendritic cells, macrophages, NK cells, CD4+ and CD8+ T cells." (PMID 39458595, 2024). "In CCA, CD8+ T lymphocytes are predominantly located within the tumor tissue, while CD4+ TILs are more prevalent in the surrounding peri-tumoral region." (PMID 39335203, 2024). "In such architecture, CD8+ T cells tended to aggregate around themselves and CD4+ T cells instead of approaching tumor cells." (PMID 38611111, 2024). "To validate the effects of DSP-0509 on Tregs, we isolated splenic Tregs and CD4+ T cells from CT26 tumors in tumor-bearing mice and subjected them to co-culture in order to assess the growth of CD4+ T cells." (PMID 39346737, 2024). "One way in which CD4+ T cells influence tumors is by facilitating the entry of CD8+ T cells into the tumor site and the infected mucosa; CD4+ T cells are also necessary for the inhibition of angiogenesis at the tumor site." (PMID 38509982, 2024). "One study showed that increased S1PR1 in CD4+ T-cells promotes STAT3 activation and JAK/STAT3-dependent Treg tumor migration, while ablation of STAT3 in T-cells reduces tumor-associated Treg accumulation and tumor migration." (PMID 38542328, 2024). "We observed that CD8+ T cells, as well as CD4+ T cells, M1 macrophages, and M2 macrophages were rare (and were only present in tumor stroma of P1-P5), indicating apparent immune escape in both metabolism-type and kinase-type PCCs." (PMID 38407266, 2024). "This combination enhanced the in vivo anti-tumor effect and increased splenic CD4+Ki-67+ helper and CD8+Ki-67+ cytotoxic T lymphocytes, and tumor-infiltrating CD3+CD4+ helper and CD3+CD8+ cytotoxic T lymphocytes." (PMID 38558795, 2024). "A slight increase in CD4+ activation was determined when splenocytes from oxTAA‐vaccinated mice were co‐cultured with tumor cells." (PMID 38958560, 2024). "Regulatory CD4+ T cells are recognized as acting mostly as suppressors of anti-tumor responses, at least partially through secretion of TGF-b and IL-10, and are deemed as major contributors to the mostly immunosuppressive cytokine milieu described for NMSCs." (PMID 38891095, 2024). "In PRAD, tumor-specific CD4+ and CD8+ T cells exhibit rapid upregulation of LAG-3 upon encountering antigens in vivo." (PMID 39120585, 2024). "Among tumor-infiltrating lymphocytes, there are effector CD4+ and CD8+ T cells with strong anti-tumor properties as well as Treg cells, which play an important role in immune suppression." (PMID 38791951, 2024). "Although CD8+ T cells are mostly connoted with cytotoxic and tumoricidal activities, namely, in NMSCs, a wealth of past research has disclosed a major role also for CD4+ T cells in tumor immune surveillance with relevance to prognosis." (PMID 38891095, 2024).
tumor (continued). "Within the tumor microenvironment, altered lipid metabolism promotes cancer cell malignancy by activating oncogenic cascades; however, impact of lipid metabolism in CD4+ tumor-infiltrating lymphocytes (TILs) remains poorly understood." (PMID 39543650, 2024). "Our results suggest that cryoablation of the primary tumor can not only increase the expression of PD-L1, but also promote the infiltration of CD8+ T cells and increase PD-1 expression on the surface of CD8+ T cells and CD4+ T cells within the secondary tumor." (PMID 39489086, 2024). "DSCC1 expression also has a substantial positive association with the presence of immune cell types (CD8+ T cells, CD4+ T cells, and B cells), possibly altering the tumor microenvironment and leading to cancer development." (PMID 39768811, 2024). "Tumor cells were left untreated (control) or were treated with an HVEM blocker before co-culturing with CD4+ T cells in vitro in a carboxyfluorescein succinimidyl ester (CFSE)-dependent proliferation assay." (PMID 38785930, 2024). "c-DC1s are known to have a central function in the TME by leveraging their ability to cross-present (cross-priming) tumor-associated antigens (TAAs), eliciting a robust CD4+ and CD8+ T cell-mediated anti-tumor immune responses involving both MHC-I and II." (PMID 39609700, 2024). "As key helper cells in tumour cell immunity, CD4+ T cells have dual regulatory functions by either promoting or suppressing CD8+ T‐cell immune responses." (PMID 38468489, 2024). "The combination of the 3D hydrogel scaffolds (CTX and CpG/tumor-lysate) resulted in significantly advanced immune responses promoting the downregulation of CD4+ T cells and the upregulation of CD8+ T cells." (PMID 38791452, 2024). "The results showed that the numbers of tumor-infiltrating CD4+ and CD8+ T cells were significantly elevated after viral treatment, compared with PBS treatment." (PMID 38473379, 2024). "By facilitating CD8+ T cell priming or migration to the tumor site, CD4+ T cells contribute to tumor rejection." (PMID 38745661, 2024). "A recent study has reported a new function of CD4+ T cells for the first time, in which one specific subtype of CD4+ T cells kills tumor cells that escape CD8+ T cell attack." (PMID 38482008, 2024). "Later studies in syngeneic mouse tumor models confirmed that VbP required CD4+, CD8+, and CD11c+ cells to achieve maximal efficacy." (PMID 38391959, 2024). "In the untreated control group, the scarcity of CD8+, CD4+ T lymphocytes, and eosinophils penetrating the tumor mass indicated a limited immune response within the tumor microenvironment." (PMID 38524132, 2024). "According to the authors, PANoptosis boosts tumor-specific immunity and positively correlates with infiltration of immune cells such as CD4, CD8, and NK cells in the TME." (PMID 38169587, 2024). "Further, within both CD8+ and CD4+ T cells – both within the tumor and spleen – we observed a shift towards Ki67+CD69+ and Ki67+PD-1+ cells, indicating the prevalence of both proliferating and activated lymphocytes in response to AP-diABZI." (PMID 38766114, 2024). "Most importantly, we were able to colocalize the 89Zr-mCD4-Mb distribution to endogenous tumor-infiltrating CD4+ cells by secondary staining of the Mb, highlighting the tracer-specific targeting of CD4+ cells within the TME at the cellular level." (PMID 39239511, 2024). "In the immune microenvironment of EC, tumor-elicited immunosuppression is mainly due to the conjugation of over-expressed PD-L1 and PD-L2 on EC cells to PD-1 receptors on tumor-infiltrating CD4+/ CD8+ T cells." (PMID 38811811, 2024). "Apart from that, in HCC patients, CD4+CD25+ regulatory T cells (Tregs) are significantly increased in tumor-infiltrating lymphocytes and peripheral blood monocytes." (PMID 38240856, 2024).
tumor (continued). "Mechanistic insights revealed that ELP treatment modulated the tumor immune microenvironment, leading to increased activation of CD4+ and CD8+ T cells, as well as polarization of tumor-associated macrophages towards the M1 phenotype." (PMID 38612457, 2024). "These cell suspensions contained malignant CD4 + Thf-like cells, which express PD1 and CXCR5, and the associated tumor microenvironment consisting of germinal center (GC) B cells and CD8 TILs." (PMID 39272178, 2024). "Expression of TIGIT was increased in tumor-infiltrating T cells, especially in DUSP4hi CD4 and CD8 T cells, compared to reference T cells from blood." (PMID 38181797, 2024). "Multiplex‐IF analysis in the humanized mice showed that PI3K/mTORi‐treated tumours displayed higher CD4+ and CD8+ T‐cell infiltration in the tumour bed and lower pS6S240/244 levels, compared to vehicle‐treated tumours." (PMID 38711203, 2024). "Once activated by antigen-presenting cells (APCs), CD4+ T cells can rapidly differentiate into different subtypes: CD4+ effector T cell (Teff) exhibits anti-tumor activity, and regulatory T cell (Treg) has immunosuppressive and tumor-promoting effects." (PMID 38415258, 2024). "Strikingly, even though the TILs injected were primarily CD8 positive, the T cells remaining in liver and spleen after tumor eradication were primarily CD4+ positive cells." (PMID 39312285, 2024). "In this study, we identified lymphocyte clusters composed of TIBs and CD4+ T cells predominantly located within the perivascular niche along tumor margins or stroma of GIBMs, which we interpreted as TLSs." (PMID 39594720, 2024). "Prior studies have elucidated that antigen-specific CD4+ T cells contribute to anti-tumor immunity by aiding CD8+T cells." (PMID 39372398, 2024). "Overall, these data demonstrate that specific Flot2 deficiency in T cells boosts antitumor responses of both CD4+ and CD8+ T cells in murine tumor models." (PMID 39499901, 2024). "Increased accumulation of TNF-α producing CD4+ Th cells in the tumor microenvironment was also observed in mice after treatment." (PMID 38920557, 2024). "CD4 T cells also have effector roles in the tumor microenvironment including direct cytotoxicity, cytokine secretion, and NK cell activation." (PMID 39538331, 2024). "Immunohistochemistry staining revealed a significant reduction in the infiltration of Cd4+ T cells, Cd8+ T cells, and Cd56+ NK cells in the tumor tissue of the KO group, whereas αSma-expressing fibroblasts were more abundant." (PMID 38942797, 2024). "CD8+ T cells release interferon-γ to elicit an anti-tumor immune response, and CD4+ T cells form a part of the adaptive immune system and are expressed on the host cell surface bound to MHC molecules." (PMID 38540119, 2024). "Here, we found that CCA and HCC patients display decreased levels of CD4+ Treg circulating in the blood, which are restored one month after the surgical resection of the tumor." (PMID 39408071, 2024). "This was accompanied by an increase in tumor-infiltrating CD4+ and CD8+ T cells, including IFN-γ-producing CD8+ T cells." (PMID 39493763, 2024). "This score was positively correlated with the number of immunosuppressive nTregs and negatively correlated with the infiltration scores of NK and CD4 + T-cells via tumor-killing effects." (PMID 39162904, 2024). "The role of CD4+ T cells in tumor defense has been extensively studied in animal models prior to clinical trials, as well as in patients with cancer." (PMID 39507526, 2024). "In a second study, NLR-low patients had more CD8+ and CD4+ T-cell infiltration in their tumours, a surprising finding, as CD8+ T-cell infiltration is a marker of poor outcome in mRCC." (PMID 39129249, 2024). "Our multiplex IHC and Nanostring gene expression analyses demonstrated a lower number of both CD8+ and CD4+ T cells in FLCs than in NTL or the tumor-NTL interface but a relatively preserved number of Tregs in tumors." (PMID 38429349, 2024).
tumor (continued). "High levels of tumor necrosis factor receptor type II (TNFR2) are preferentially expressed by immunosuppressive CD4+Foxp3+ regulatory T cells (Tregs), especially those present in the tumor microenvironment, as initially reported by us." (PMID 39247806, 2024). "Whereas, natural killer (NK) cells, dendritic cells (DCs), cytotoxic (CD8+) and helper (CD4+) T cells are considered essential for tumour cell killing, and mounting a potent and sustained anti-tumour immune response." (PMID 39641590, 2024). "Our data showed that CD8Tex, Treg, Th1, and Tprolif are majorly originated from tumor tissues, whereas CD4+T and NK cells are predominantly isolated from PBMCs." (PMID 39575251, 2024). "Immunohistochemistry was used to evaluate the expression of PD-L1 and tumor microenvironment cells (CD4, CD8, CD68 and CD163)." (PMID 39123373, 2024). "The removal of α-SMA+ myCAFs in PDAC hindered tumor immune surveillance, resulting in an elevated percentage of regulatory T cells (Treg, CD4+Foxp3+)." (PMID 38540204, 2024). "For example, strong interactions existed between the tumor cells and B cells, CD4+ T cells, CD8+ T cells or Tregs through the lymphotoxin and lymphotoxin beta receptor (LTB-LTBR)." (PMID 38191598, 2024). "The generated heatmap showed that the hallmark pathways in CD4+ T_C2 were activated in the EMT and TNFA signaling pathways via NF-κB, which promotes tumor progression." (PMID 38918785, 2024). "Immunocompromised tumor environment due to natural suppressor cells like CD4+ CD25+ T cells is one of the major reasons for tumor progression and malignancy." (PMID 38571964, 2024). "Classically, CXCL13 coordinates B cells, which in combination with CXCL13 producing CD4+ T cells and other tumor-reactive T cells results in the formation of tertiary lymphoid structures (TLS)." (PMID 38786066, 2024). "T-helper type 9 (Th9) cells are a subset of CD4+ effector T cells with robust and persistent anti-tumor effects." (PMID 38760861, 2024). "Patients with a high frequency of CN3 showed significantly higher spatial scores than those with a low frequency of CN3, suggesting that CD4+ T cells suppressed the proximity of CD8+ T cells to tumor cells in the lymphocyte enrichment region." (PMID 38611111, 2024). "One BRIT tumor sample showed high γH2AX activity, STING activation, CD8+ T-cell infiltration, CD4+ T-cell infiltration, and strong CD163+ tumor-associated macrophage populations." (PMID 39669575, 2024). "Comparing the proportions of T/NK cells between normal and tumor groups revealed an enrichment of the four CD4+ T cell clusters, two exhausted CD8+ T cell subsets, and CD8+ZNF683+ Trm cells in the tumor group." (PMID 39093451, 2024). "First, we examined the ratio of tumour infiltrating CD4/CD8+ T cells in PCa models using flow cytometry and multiplex IHC." (PMID 39390760, 2024). "Overall, cDC2 contributes to anti-tumor immunity by TAA presentation to CD4+ T cells or the transfer of TAAs to lymphoid tissue-resident DCs but is dependent on cDC1 function and the presence of Tregs." (PMID 38261139, 2024). "Our data suggest that this increase in intratumoral Tregs is driven by two processes – direct conversion of CD4+ T cells and increased infiltration of Tregs into the tumor." (PMID 39091728, 2024). "Both oAd/APP and oAd/APP+DC treatment induced higher level of CD4- or CD8-positive T cell infiltration into tumor tissues than PBS or DC treatment, with oAd/APP+DC leading to more robust infiltration than oAd/APP monotherapy." (PMID 38835775, 2024). "Particularly, CD4+ tumor-infiltrating cells displayed an HLA-DR MHC class II phenotype and interacted with “ionized calcium-binding adaptor molecule 1” (IBA1)-positive antigen-presenting cells (APCs)." (PMID 39202398, 2024).
tumor (continued). "The effectiveness of therapeutic cancer vaccines is now being improved by enhancing tumor specific CD4+ T-cell responses." (PMID 38793749, 2024). "When combined with anti-PD-L1, it promoted the reactivity and sustained memory of tumor immunity via the development of Th1 in CD4+ T cells." (PMID 38229100, 2024). "No remarkable differences were observed in the proportion of tumor-infiltrating CD4+ T cells, NK cells, B cells, DCs and tumor-infiltrating macrophages." (PMID 38643157, 2024). "Depending on the expression of MHC class II molecules on the tumor cell’s surface, CD4 T cells will adopt different strategies to try to kill the cancer cells." (PMID 39493763, 2024). "The PD-1/PD-L1 interaction inhibits tumor-infiltrating CD4+/CD8+ T cells, reducing cytokine secretion and facilitating tumor immune evasion." (PMID 39628695, 2024). "Other than TAMs, Tumour-infiltrating lymphocytes (TILs) are also present in the tumour microenvironment, comprising heterogeneous populations of CD4+, CD8+ (T cells), CD20+ (B cells), NK and T regulatory cells." (PMID 40176927, 2024). "Inclusion of these CD4+ T cell peptides in a synthetic peptide vaccine containing CD8+ T cell neo-epitopes improved survival of tumor-bearing mice." (PMID 39040850, 2024). "CD4+ T-helper cells have the potential to enhance anti-tumor immune responses by secreting cytokines, such as IFN-γ." (PMID 38169970, 2024). "In one of the patients from each of the lead-in groups (A-2 and S-2), increases in CD19+ tumor-infiltrating B cells, CD68+ tumor-associated macrophages, CD4+ and CD8+ T cells (CD3+), as well as FOXP3+ regulatory T cells, were also observed." (PMID 38672538, 2024). "We examined the distribution of lymphocytes in GIBMs and identified clusters of TIBs and CD4+ T cells in the tumor stroma that exhibited distinct characteristics from those of TLSs in primary GI cancers." (PMID 39594720, 2024). "Our ongoing investigation aims to explore the interaction between these two disulfidptosis-related CD4+ T cell subgroups and tumor cells, along with their mechanisms of exerting pro-oncogenic functions." (PMID 38292868, 2024). "CD4+ T cells contribute to the regulation of immune responses by influencing the activation of CD8+ T cells which recognize tumor antigens and execute cytotoxic functions." (PMID 38349050, 2024). "IL-18 was shown to promote MDSC accumulation in the tumor microenvironment, leading to the suppression of CD4+ and CD8+ T cells, both in solid tumors and hematologic malignancies." (PMID 38397043, 2024). "In this study, a mouse tumor model Hepa1-6, which is sensitive to CD4+ T cell activity, was used to conduct mechanistic analysis of an anti-CTLA-4 Ab." (PMID 39106430, 2024). "TGF-β also incites polarization of CD4+ cells into regulatory T cells, which directly inhibit cytotoxic T cell mediated anti-tumor responses." (PMID 38822345, 2024). "Tumor-infiltrating lymphocytes (TILs), which include CD4+ helper cells and CD8+ cytotoxic T-cells (CTLs), represent the adaptive immune response in the TME." (PMID 38542199, 2024). "This systematic review highlights the immunosuppressive tumor microenvironment in HBV-associated HCC, characterized by dysfunctional and exhausted HBV-specific T cells and increased infiltration of HBV-specific CD4+ T cells, particularly Tregs." (PMID 38793588, 2024). "Recent studies have highlighted the potential of these CD4 cells to not only support CD8 activation but to mediate direct cytotoxic killing of MHC-II-expressing tumour cells." (PMID 38811992, 2024). "Whole-tumor cell vaccinations also offer entire antigens in comparison to peptidic fragments, which are capable of stimulating both CD4 and CD8 T cell, as well as B cell responses, providing a broad effector repertoire." (PMID 39840067, 2024).